SPRY2 (sprouty RTK signaling antagonist 2)
Diseases named in the same sentence as SPRY2 in open-access papers (continued):
Sharing a sentence is not in itself a finding about the gene and the disease.
colon carcinoma (continued). "In addition, in colon cancer, Spry2 functions as an oncogene via up-regulation of c-Met expression." (PMID 26976794, 2016). "Interestingly, in contrast to our results, SPRY2 can suppress both basal and 1α,25-dihydroxyvitamin D3-induced E-cadherin expression, and SPRY2 expression levels are negatively correlated with E-cadherin expression levels in human colon cancer cells." (PMID 27835572, 2016). "With Spry2 transfectants forming significantly larger xenografts with higher metastatic potential in vivo, they concluded that Spry2 may control metastatic potential of colon cancer cells, at least in part, by c-Met upregulation." (PMID 24744103, 2014). "For example, we have previously demonstrated that SPRY2 negatively regulates miR-194, leading to increased AKT2 protein in colon cancer cells." (PMID 34685612, 2021). "In vitro, overexpressed Spry2 inhibited the growth and migration of HCT116 human colon cancer cells which was concomitantly accompanied by an increase in the expression of PTEN and reduction in phosphorylation of ERK and Akt." (PMID 24744103, 2014). "Spry2, for example, is above its function in GBM, shown to promote colon cancer malignancy by increasing proliferation, migration, tumor growth and invasion of colon cancer cells." (PMID 31374860, 2019). "We established that concurrent suppression of SPRY1 and SPRY2 may have additional effects in decreasing EMT markers or EMT-inducing transcription factors and thus favoring epithelial phenotype in colon cancer cells." (PMID 26434583, 2016). "To determine whether SPRY2 regulates EMT in colon cancer cells, we selected HCT116 and SW480 human colon cancer cell lines that contained different levels of endogenous SPRY2 protein expression." (PMID 26434583, 2016). "They showed that the expression of Spry2 positively correlates with the sensitivity of colon cancer cells to the EGFR inhibitor gefitinib and that Spry2 can enhance the response of colon cancer cells to gefitinib by increasing the expression of phosphorylated EGFR, total EGFR, and PTEN." (PMID 24744103, 2014).
colorectal cancer (11 papers, 2010 to 2025). A primary or metastatic malignant neoplasm that affects the colon or rectum. "Despite being tumor suppressors in many types of cancer, SPRY1 is an oncogene in rhabdomyosarcoma, SPRY2 in colorectal cancer, and SPRY4 in gastric cancer." (PMID 41516252, 2025). "In colorectal cancer, SPRY2 was proved to repress epithelial-mesenchymal transition and cell proliferation, while some other evidence proved that SPRY2 high-expression indicated poorer prognosis." (PMID 28002800, 2017). "Sprouty (SPRY) appears to act as a tumor suppressor in cancer, whereas we demonstrated that SPRY2 functions as a putative oncogene in colorectal cancer (CRC) (Oncogene, 2010, 29: 5241–5253)." (PMID 26434583, 2016). "SPRY2 inhibits the RAS/MAPK/ERK pathway and is a potential study target for colorectal cancer and IgG nephropathy." (PMID 40141227, 2025). "In contrast, in colorectal cancer (CRC), we have reported Spry2 upregulation in high-grade tumors and at the invasion front of low-grade tumors, where the levels of Spry2 RNA and protein are higher in colon adenocarcinomas than in the adjacent normal mucosa." (PMID 37045830, 2023). "We reported, for the first time, that increased expression of SPRY2 augments cancer phenotype and Epithelial-Mesenchymal-Transition (EMT) in colorectal cancer (CRC)." (PMID 34685612, 2021). "Spry2 downregulation in colorectal epithelium inhibits EMT and serves as a biomarker for poor prognosis of colorectal cancer." (PMID 27415760, 2016). "As for the mechanism of miR-21 mediates VEGF expression and angiogenesis, recent studies have shown that miR-21 increases VEGF expression via ERK and AKT signal in vascular endothelial cells; miR-21 promotes angiogenesis by targeting SPRY2 and/or KRIT1 in osteoarthritis and colorectal cancer." (PMID 35586052, 2022). "With respect to colorectal cancer (CRC), we demonstrated, for the first time, upregulation of SPRY2 in CRC and inflammatory bowel disease (IBD) along with an oncogenic role of SPRY2 in CRC." (PMID 34685612, 2021). "Ten of these genes (WDR67, RFXAP, RP11-50D16.3, CAB39L, THSD1, SPRY2, TGDS, CLDN10, SLC10A2, CD33L3) have been reported changed in tumor tissues, while only 2 (RP11-50D16.3, SLC10A2) have been reported to appear changed in colorectal cancer." (PMID 20467480, 2010).
ovarian carcinoma (9 papers, 2012 to 2024). A malignant neoplasm originating from the surface ovarian epithelium. "The downregulation of miR-21 and upregulation of SPRY2 are observed in conjunction with a considerable inhibition of ovarian cancer cell growth caused by GAS5 overexpression." (PMID 39337410, 2024). "This study reveals that SPRY2 acts as a tumor suppressor in human ovarian cancer and illustrates the underlying mechanisms that can be used as possible targets for the development of novel therapeutics." (PMID 27835572, 2016). "They showed that treatment with AREG upregulates sprouty RTK signaling antagonist 2 (SPRY2) expression by activating the EGFR-mediated ERK1/2 signaling pathway in ovarian cancer." (PMID 33922533, 2021). "Overexpression of GAS5 inhibited the proliferation of ovarian cancer cells, resulting in decreased expression of miR-21 and increased SPRY2." (PMID 34204094, 2021). "SPRY2 acts as tumor suppressor in BrCa by inhibiting the Ras/Mitogen-Activated Protein Kinase Pathway, and in ovarian cancer, through inhibition of Amphiregulin (AREG)-induced cell invasion." (PMID 32005108, 2020). "In the present study, we show that treatment with AREG up-regulated SPRY2 expression by activating the EGFR-mediated ERK1/2 signaling pathway in two human ovarian cancer cell lines, SKOV3 and OVCAR5." (PMID 27835572, 2016). "The current study showed that treatment with AREG up-regulated SPRY2 expression in two human ovarian cancer cell lines, SKOV3 and OVCAR5." (PMID 27835572, 2016). "A recent study shows that SPRY2 is down-regulated in human ovarian cancer and that SPRY2 expression levels are negatively correlated with cell proliferation." (PMID 27835572, 2016). "AREG treatment similarly up-regulated SPRY2 expression in another human ovarian cancer cell line, OVCAR5." (PMID 27835572, 2016). "Our previous study and others' studies have shown that SPRY2 expression is down-regulated in human ovarian cancer and that patients with low SPRY2 expression have significantly poorer survival than those with high SPRY2 expression." (PMID 27835572, 2016). "To examine the relationship between SPRY2 expression and the survival of patients with ovarian cancer, we queried the Cancer Genome Atlas (TCGA) Research Network dataset." (PMID 27835572, 2016). "SPRY2 expression levels are down-regulated in human ovarian cancer, and patients with low SPRY2 expression have significantly poorer survival than those with high SPRY2 expression." (PMID 27835572, 2016). "Future studies will be needed to investigate the molecular mechanisms underlying the different roles of SPRY2 and SPRY4 in the regulation of EGFR-mediated cellular function in human ovarian cancer." (PMID 27835572, 2016). "SPRY2 expression levels have been shown to be down-regulated in human ovarian cancer, and patients with low SPRY2 expression have significantly poorer survival than those with high SPRY2 expression." (PMID 27835572, 2016). "Our investigation unveiled the differential expression of Spry1 and Spry2 proteins in a range of human epithelial ovarian cancer cell lines." (PMID 23251157, 2012). "Collectively, our study unveiled the differential expression of Spry1 and Spry2 proteins in various ovarian cancer cell lines." (PMID 23251157, 2012). "Initial studies were carried out to investigate the expression of Spry1 and Spry2 proteins in seven commonly-used human epithelial ovarian cancer cell lines by western blot analysis using Spry1 and Spry2 specific antibodies." (PMID 23251157, 2012). "As an initial attempt, we aimed in this study to evaluate the expression pattern of Spry1 and Spry2 isoforms in a panel of human epithelial ovarian cancer cell lines." (PMID 23251157, 2012). "In the present study we investigated the expression of Spry1 and Spry2 isoforms in a panel of human ovarian cancer cell lines in vitro." (PMID 23251157, 2012).
ovarian carcinoma (continued). "Our results also indicate the differential expression of Spry1 and/or Spry2 across the ovarian cancer cell lines studied." (PMID 23251157, 2012). "Moreover, miR-21 was found overexpressed, while SPRY2 was found downregulated in ovarian cancer-derived A2780 cells." (PMID 34204094, 2021). "Treatment with AREG up-regulates SPRY2 expression in two human ovarian cancer cell lines." (PMID 27835572, 2016). "In addition, we showed that overexpression of SPRY2 attenuated AREG-induced ovarian cancer cell invasion." (PMID 27835572, 2016). "Given the evidence that AREG plays more important roles than EGF in the regulation of ovarian cancer progression, it is interesting and important to examine whether SPRY2 can be regulated by AREG and whether SPRY2 also affects the biological functions of AREG." (PMID 27835572, 2016). "Despite the importance of AREG and EGFR in ovarian tumorigenesis, whether SPRY2 is regulated by AREG and whether SPRY2 is involved in ovarian cancer progression are still unknown." (PMID 27835572, 2016). "Therefore, the down-regulation of SPRY2 in ovarian cancer decreases its ability to inhibit EGFR-mediated cellular functions, which subsequently contributes to tumor progression." (PMID 27835572, 2016). "Since SPRY2 expression is down-regulated in human ovarian cancer, we examined whether AREG-induced E-cadherin down-regulation can be attenuated by overexpressing SPRY2." (PMID 27835572, 2016). "Thus, the GAS5/miR-21/SPRY2 signaling pathway could be a viable target for treatment in ovarian cancer." (PMID 39337410, 2024). "Therefore, through the more thorough dissection of the targets or signaling pathways that are regulated by SPRY2 could lead to the development of alternative therapeutic approaches for human ovarian cancer." (PMID 27835572, 2016). "Also, our results showing the difference in subcellular localization between Spry1 and Spry2 isoforms might be of functional significance in ovarian cancer." (PMID 23251157, 2012). "The luciferase experiment revealed that, in ovarian cancer-derived A2780 cells, miR-21 was directly targeted by GAS5, and that its target gene was SPRY2." (PMID 39337410, 2024). "The data shown in the present study demonstrated that overexpression of SPRY2 attenuated AREG-induced down-regulation of E-cadherin and invasion of human ovarian cancer cells." (PMID 27835572, 2016). "We have shown that treatment with EGF up-regulates SPRY2 expression, and overexpression of SPRY2 attenuates EGF-induced E-cadherin down-regulation and cell invasion in human ovarian cancer cells." (PMID 27835572, 2016). "In the present study, we provide new evidence that SPRY2 can antagonize the AREG-induced down-regulation of E-cadherin and invasion of human ovarian cancer cells." (PMID 27835572, 2016). "Thus, by first suppressing the expression of miR-21 and then upregulating the expression of SPRY2, GAS5 inhibits the proliferation of ovarian cancer cells." (PMID 39337410, 2024). "Additionally, in osteosarcoma and in ovarian cancer, a tumor-suppressing role for Spry2 but not Spry4 was explicitly highlighted." (PMID 31374860, 2019).
osteosarcoma (8 papers, 2014 to 2025). A usually aggressive malignant bone-forming mesenchymal neoplasm, predominantly affecting adolescents and young adults. "Although in osteosarcoma-derived cell lines Spry2 protein shows excellent tumour-suppressing properties, Spry4 neither interferes with cell proliferation nor migration in the same experimental setting." (PMID 40806483, 2025). "The largest absolute difference between tumor types was a 2.9-fold increase of SPRY2 methylation in osteosarcomas relative to clear cell sarcomas of the kidney." (PMID 35707123, 2022). "Along with an inhibitory effect on proliferation and differentiation of osteoblasts, Spry2 decelerates proliferation and migration of osteosarcoma." (PMID 34769378, 2021). "The influence of Spry2 and Spry4 on the malignant phenotype of osteosarcoma is already investigated." (PMID 34769378, 2021). "In an earlier study, we observed that Spry2 inhibits cell proliferation of osteosarcoma-derived cell lines." (PMID 27513462, 2016). "Spry2 regulates proliferative and migratory pathways in osteosarcoma and endothelial cells." (PMID 37097161, 2023). "Furthermore, it is known that Spry2 exerts a strong tumor-suppressing activity in osteosarcoma, and Spry3 could interfere with this action." (PMID 34769378, 2021). "In an earlier study in osteosarcoma-derived cells, we observed that Spry2 could function as a tumor suppressor, while Spry4 had no influence on the malignant phenotype of the cells." (PMID 27513462, 2016).
glioblastoma (7 papers, 2012 to 2025). The most malignant astrocytic tumor (WHO grade IV). "SPRY2 was upregulated in glioblastoma, and overexpression of SPRY2 is associated with human oral squamous-cell carcinogenesis." (PMID 36077151, 2022). "In glioblastoma, Spry3 and Spry2 have a tumour-promoting potential, while Spry4 was shown to interfere with malignant features of glioblastoma." (PMID 40806483, 2025). "In this study, we uncover SPRY2-dependent bypass signaling mechanisms in glioblastoma that contribute to resistance against EGFR and MET (hepatocyte growth factor receptor) inhibition." (PMID 41567627, 2025). "In contrast, the role of Spry3 is only studied in glioblastoma, where it is like Spry2 functioning as tumor promoter." (PMID 34769378, 2021). "In contrast, the antitumoral effect achieved by Spry2 silencing in glioblastoma is based on excessive activation of ERK signaling." (PMID 34769378, 2021). "The authors concluded that an antitumoral effect of SPRY2 inhibition is based on excessive activation of ERK signaling and DNA damage response, resulting in reduced cell proliferation and increased cytotoxicity, proposing SPRY2 as a promising pharmacological target in glioblastoma patients." (PMID 34685488, 2021). "In this study, we analyzed the effects of SPRY2 on endocytosis and degradation of FGF receptor 1 (FGFR1) using two human glioblastoma (GBM) cell lines with different endogenous SPRY2 levels." (PMID 39682716, 2024).
endometrial carcinoma (6 papers, 2012 to 2024). A malignant tumor arising from the epithelium that lines the cavity of the uterine body. "Parts of the FGF and RAS-MAPK pathways are changed in endometrial cancer, and expression of SPRY2 is reduced due to hypermethylation in several types of cancer." (PMID 22548175, 2012). "SPRY2 expression is extremely low in advanced invasive cancers and other types of endometrial cancer, other than endometrioid adenocarcinoma, which indicates that SPRY2 may play a role in suppression of endometrial cancer by regulating the MAPK pathway." (PMID 22548175, 2012). "These are ERRFI1, IL6, PIK3R1 and SPRY2 which were found to be upregulated and YWHAZ which was found to be downregulated; Endometrial cancer has twelve genes." (PMID 34764329, 2021).
liver cancer (6 papers, 2019 to 2025). An epithelial or non-epithelial malignant neoplasm that arises from the liver. "For instance, miR-330-5p activates the MAPK/ERK signaling pathway by regulating the expression of SPRY2, thereby promoting the progression of liver cancer." (PMID 40533863, 2025). "Previous studies have demonstrated that SPRY2 acts as a tumor suppressor in diverse types of human cancers, such as non-small cell lung cancer, liver cancer, colon cancer, and breast cancer." (PMID 30837325, 2019). "Similarly, transwell assay and CCK8 assay results indicated that the knockdown of SPRY2 in liver cancer cells relieved the inhibitory effects of anti-miR-27a-3p on cell proliferation and migration." (PMID 39742261, 2024). "Inactivation of SPRY2 has been reported to activate MAPK and PKM2 pathways and accelerate liver cancer development." (PMID 37507768, 2023). "Overall, our study revealed a novel miR-22-3p/CBL/SPRY2/ERK axis that plays an important role in EMT, cell migration, and invasion of liver cancer cells." (PMID 36749775, 2023). "By inhibiting the expression of CBL, which stabilizes SPRY2, miR-22 indirectly upregulates SPRY2, thereby suppressing the epithelial-mesenchymal transition (EMT), cell migration, and invasion and decreasing the expression of liver cancer stem cell (CSC) marker genes." (PMID 36749775, 2023).
multiple myeloma (6 papers, 2015 to 2023). "The aim of the present study was to assess the effects of sprouty homolog 2 (SPRY2) gene regulation by miR-21 on the occurrence, development and tumor metastasis in multiple myeloma (MM)." (PMID 25825239, 2015). "Besides, it is also reported that miR-21 decreased cell migration and invasion of multiple myeloma cells by down-regulating sprouty homolog 2 (SPRY2) gene expression." (PMID 33026076, 2020). "The aim of the present study was to investigate the expression level of microRNA 21 (miR-21) in the peripheral blood of patients with multiple myeloma (MM) and to investigate the correlation between miR-21 and sprouty homolog 2 (SPRY2) gene expression levels in MM." (PMID 25633921, 2015).